CREB3L2 (cAMP responsive element binding protein 3 like 2)
Description:
Transcription factor involved in unfolded protein response (UPR). In the absence of endoplasmic reticulum (ER) stress, inserted into ER membranes, with N-terminal DNA-binding and transcription activation domains oriented toward the cytosolic face of the membrane. In response to ER stress, transported to the Golgi, where it is cleaved in a site-specific manner by resident proteases S1P/MBTPS1 and S2P/MBTPS2. The released N-terminal cytosolic domain is translocated to the nucleus to effect transcription of specific target genes. Plays a critical role in chondrogenesis by activating the transcription of SEC23A, which promotes the transport and secretion of cartilage matrix proteins, and possibly that of ER biogenesis-related genes (By similarity). In a neuroblastoma cell line, protects cells from ER stress-induced death. In vitro activates transcription of target genes via direct binding to the CRE site.
Synonyms: BBF2H7; TCAG_1951439
Tractability: Antibody: UniProt predicts a signal peptide or a membrane-spanning region. PROTAC: UniProt records ubiquitination sites on it; ubiquitination databases record sites on it.
Gene: Protein-coding gene on chromosome 7 (137,874,979 to 138,002,086, reverse strand). Ensembl gene ENSG00000182158.
Subcellular location: Endoplasmic reticulum membrane; Nucleus (Processed cyclic AMP-responsive element-binding protein 3-like protein 2)
Subcellular location (Human Protein Atlas): Endoplasmic reticulum; Nucleoplasm
Pathways (Reactome):
Cellular responses to stimuli: CREB3 factors activate genes
Gene Ontology:
Molecular function: cAMP response element binding; transcription cis-regulatory region binding; DNA-binding transcription factor activity, RNA polymerase II-specific; DNA-binding transcription activator activity, RNA polymerase II-specific; DNA-binding transcription factor activity; RNA polymerase II cis-regulatory region sequence-specific DNA binding
Biological process: positive regulation of DNA-templated transcription; response to endoplasmic reticulum stress; cartilage development; chondrocyte differentiation; regulation of transcription by RNA polymerase II; endoplasmic reticulum to Golgi vesicle-mediated transport; positive regulation of transcription by RNA polymerase II; regulation of DNA-templated transcription
Cellular component: endoplasmic reticulum; nucleoplasm; nucleus; chromatin; endoplasmic reticulum membrane
Genetic constraint (gnomAD): Loss-of-function variants: 22 observed, 48.72 expected, observed/expected ratio (o/e) 0.45, 90% interval 0.32 to 0.64. The upper end of that interval is the gene's LOEUF score, 0.64, which puts it in group 2 of 6, group 1 being the genes least tolerant of losing a copy. Missense variants: 583 observed, 579.9 expected, observed/expected ratio (o/e) 1.01, 90% interval 0.94 to 1.08. Synonymous variants: 258 observed, 247.56 expected, observed/expected ratio (o/e) 1.04, 90% interval 0.94 to 1.15.
Cancer hallmarks: proliferative signalling (promotes)
Homologues: Orthologues: chimpanzee CREB3L2 (99% identical), macaque CREB3L2 (99% identical), dog CREB3L2 (95% identical), pig CREB3L2 (94% identical), guinea pig CREB3L2 (92% identical), mouse Creb3l2 (91% identical), rabbit CREB3L2 (79% identical), tropical clawed frog CREB3L2 (58% identical), zebrafish creb3l2 (53% identical), Drosophila melanogaster CrebA (27% identical), Caenorhabditis elegans crh-2 (16% identical), Caenorhabditis elegans atf-6 (13% identical), and 3 more. Paralogues in human: CREB3L1 (43% identical), CREB3L3 (22% identical), CREB3L4 (19% identical), ATF6B (18% identical), CREB3 (17% identical), ATF6 (15% identical), CREM (11% identical), ATF1 (11% identical), CREB1 (10% identical).